NR2F1-AS1 (NR2F1 regulatory antisense RNA 1)
Synonyms: NAS1; FLJ42709
Gene: Long non-coding RNA gene on chromosome 5 (93,360,779 to 93,585,649, reverse strand). Ensembl gene ENSG00000237187.
Diseases named in the same sentence as NR2F1-AS1 in open-access papers:
NR2F1-AS1 is named in the same sentence as 1 disease in open-access papers, as found by Europe PMC text mining. Sharing a sentence is not in itself a finding about the gene and the disease. The quoted sentences say what the papers report.
non-small cell lung carcinoma (1 paper, 2022). A group of at least three distinct histological types of lung cancer, including non-small cell squamous cell carcinoma, adenocarcinoma, and large cell carcinoma. "Long noncoding RNA (lncRNA), specifically the upregulation of lncRNA NR2F1 antisense RNA 1 (NR2F1-AS1), has been involved in the progression of non-small cell lung cancer (NSCLC), but the mechanisms that underlie this remain unclear." (PMID 34993348, 2022).